TNF (tumor necrosis factor)
Diseases named in the same sentence as TNF in open-access papers (continued):
Sharing a sentence is not in itself a finding about the gene and the disease.
infection (continued). "A possible role of IGF-I and TNF-α in infection and the capability of the host to cope with tissue damage has been previously demonstrated by treating developing rainbow trout, prior to infection with Yersinia ruckeri, with 17β-estradiol (E2)." (PMID 26821056, 2016). "Several fungus-related virulence factors, such as polysaccharide capsule, melanin, and prostaglandinlike molecules, have been documented to inhibit the stimulation of TNF-α during wild-type C. neoformans infection (41, –, 43)." (PMID 27165801, 2016). "Comparison of the human and chicken H7N9 viruses showed that H7N9-HU induced significantly higher levels of TNF-α at 12 h post-infection, and significantly higher levels of IL-8 from 12 to 48 h post-infection than those of H7N9-CK." (PMID 26975414, 2016). "Four week following aerosol infection, IL-21R−/− T cells are reduced in the blood and lungs relative to WT T cells, and produce less IFNγ and TNF, similar to experiments performed with IL-12R−/− CD8+ T cells." (PMID 27819295, 2016). "TNF-α is secreted as part of an acute phase reaction to mediate protective immune responses to infection." (PMID 27493792, 2016). "Tumor necrosis factor alpha (TNF-α is another important cytokine that mediates host response to infections." (PMID 27150018, 2016). "This response increased (160%) at 1 h of infection and reached an increase of 185% at 2 and 4 h of infection with respect to those induced by TNF-α alone." (PMID 27774437, 2016). "While, at 2 and 4 h of infection the co-stimulation increased the levels of p65 phosphorylation to 320 and 340% respect to TNF-α alone." (PMID 27774437, 2016). "For CMV re-activations specifically, an increased risk for active infection in patients with double immunosuppression consisting of AZA and TNFα-inhibitors was described." (PMID 27214202, 2016). "To specifically address the phenotype and multifunctionality of responding T cells, we performed intracellular cytokine staining (ICS) for the expression of IFN-γ, TNF-α, and IL-2 following in vitro restimulation (infection strain, MOI = 0.1)." (PMID 27512056, 2016). "The levels of serum TNF-α after sacrifice were higher in the infection groups compared to the shame-infection groups (C57 mice: P < 0.01; STZ-C57 mice: P < 0.05; TH mice: P < 0.05; db/db mice: P < 0.05)." (PMID 27995146, 2016). "We found similar levels of IL-17 and IFN-γ in the colon tissues of infected WT mice and Dock2−/− mice and elevated levels of TNF in the colon tissues of infected Dock2−/− mice compared with WT mice 14 days post-infection." (PMID 27291827, 2016). "Our findings indicate that early after infection, robust IFN-γ/TNF-α responses by Tcm are associated with greater mycobacterial burden, while IFN-γ/TNF-α/IL-2 responses by Tcm cells are indicative of a protective response." (PMID 27799930, 2016). "Consistent with the data of expression of inflammatory genes in our in vitro experiment, infection with LV-VNN1 increased the plasma concentrations of TNF-α, IL-1β, and IL-6 by 32.8%, 31.8%, and 56.5%, respectively." (PMID 27281478, 2016). "One type of cytokine, TNF-α, is secreted by monocytes and macrophages and plays a prominent role in infection and inflammation." (PMID 26797392, 2016). "Coinciding with a significant increase of mycobacterial burden and pathological changes following TNFα blockade, gene array analyses of infected lungs revealed major changes of inflammatory and immune gene expression signatures 4 weeks post-infection." (PMID 27853279, 2016). "The cytokines TNF-α and IL-1β in teleosts are powerful proinflammatory cytokines released by several immune cells during infection or tissue damage and are involved in a diverse range of inflammatory and infectious conditions." (PMID 28105799, 2016). "We observed a 15-fold increase in IFN-β mRNA and a 23-fold increase in TNF-α mRNA in IIV-6-infected cells compared to mock-infected cells 24 hours post-infection." (PMID 27824940, 2016).
infection (continued). "Against this background, tumour necrosis factor alpha (TNF-α), which is a first cytokine released during infection activates the downstream expression of other cytokines such as IL-1β and chemokines." (PMID 27529219, 2016). "Infection of macrophages with M. tuberculosis induces the production of proinflammatory cytokines such as tumor necrosis factor (TNF), gamma interferon (IFN-γ), etc.." (PMID 27303736, 2016). "The site of infection also showed decreased inflammatory infiltrates and decreased cytokine expressions for IL-12, TNF-α, TGF-β and IL-10." (PMID 27579922, 2016). "The final significant parameter, TNF secretion, is negatively correlated with ECB early on in the infection, which would be expected given TNF's pro-inflammatory role." (PMID 26913242, 2016). "We therefore quantified the number of virus-specific CD8+T cells and their ability to produce intracellular cytokine IFNγ and/or TNFα day 7 after infection." (PMID 27245318, 2016). "Hamster kidney following infection with virulent Leptospira, or hamster peripheral blood mononuclear cells (PBMCs) cultured with Leptospira, upregulate TNF-α, IFN-γ, IP-10, IL-10, and IL12p40." (PMID 27486445, 2016). "Overall, cytokine production in the bladder was significantly lower in mice following infection with the β-H/C-deficient 807ΔcylE mutant compared with wt UPSA 807; only KC and TNF-α were significantly elevated above control levels detected in the PBS group." (PMID 27383371, 2016). "The second set of data is from ID 12971 for a study on TNFα cytokine expression level two days after infection with H5N1 influenza A virus." (PMID 27203862, 2016). "After infection of macrophages, only TNF-α production was significantly decreased when compared with control (P < 0.05)." (PMID 27795620, 2016). "Others showed that lipoproteins from pathogenic S. pneumoniae induces TLR2 to promote the release of TNFα from macrophages during infection." (PMID 27309732, 2016). "It has been shown that IL-6, a pleiotropic cytokine, plays a central role in the immune responses activated through the TNF-α and NF-κB pathways, as a first line of defense against infection in the acute-phase response." (PMID 26865111, 2016). "We observed that infection significantly upregulates the secretion of cytokines TNF-α, IL-1β, IL-8, MCP-1, MMP, oxidative stress, transendothelial permeability, and LDL uptake." (PMID 27582738, 2016). "The lung expresses higher amounts of IFN-α than the DLN at day 5 post-infection as well as other proinflammatory cytokines, such as IL-6 and TNF-α." (PMID 27014272, 2016). "The ratio of IFNγ+TNF+ (e.g., double producers) to total IFNγ producers fell as infection persisted." (PMID 26967901, 2016). "The average TNF-α/IL-10 cytokine ratio was 0.134 ± 0.136, and average time to first recorded infection was 5.4 ± 3.0 days post-burn." (PMID 27761434, 2016). "Our results blend into these findings since infection with C. albicans resulted in an increased TNF-α production in PBMO." (PMID 27870876, 2016). "Analysis of infection-induced cytokines, including IL-8, IL-1β, IL-6 and TNF-α in vitro and in vivo revealed that cytokine and chemokine responses were dependent on expression of β-H/C that also elicited severe bladder neutrophilia." (PMID 27383371, 2016). "Understanding the dynamics of infection-mediated iNOS production in the presence of TNF-α, IFN-γ, and the synergistic effects of both can aid in elucidating each cytokine’s contribution to NO formation and the effector response of the host." (PMID 27276061, 2016). "A1142 stimulated TNF-α and IL-6 secretion by mouse macrophage Raw 264.7 cells as detected at ~1 and ~6 h after infection." (PMID 27550826, 2016). "Infection and efficient replication of the virus in MBECs induced progression in the damage of the endothelial monolayer and TNF- α and MCP-1 production, which favored leukocyte transmigration." (PMID 27336851, 2016).
infection (continued). "Their activation results in the induction of proinflammatory mediators, such as TNFα a potent bioactive molecule commonly secreted by recruited inflammatory cells, allowing for paracrine signaling at the site of an infection." (PMID 27698456, 2016). "IGF-I and TNF-α gene expressions were lower also prior to infection already after the developmental E2-treatment." (PMID 26821056, 2016). "In the livers of animals infected with HA-MARV, the pro-inflammatory cytokines TNF-α and IL-6, as well as the Th2 cytokines IL-4 and IL-5 and the Th1 cytokine IL-12, were all elevated early before decreasing over the course of infection." (PMID 27976688, 2016). "Titers of TNF-α and IL-12 were obviously increased to 10.1 pg/mg total lysate protein and 0.2 pg/mg total lysate protein at the third day after infection with LM while production of TNF-α and IL-12 barely changed after infection with LI." (PMID 27375558, 2016). "The expression of TNF-α in largemouth bass supports the finding that the TNF-α gene is significantly expressed at early stages of infection." (PMID 27706080, 2016). "As the infection progresses however, the infected cells become less sensitive to TNFα-mediated NF-κB stimulation and undergo apoptosis." (PMID 27007501, 2016). "Seven days after infection, the expression of IL-1β, IL-6, IL-17, IL-18, and TNF-α mRNA was significantly lower in the jejunum of COS-fed mice compared to those of controls." (PMID 28100936, 2016). "Resident epithelial cells and macrophages at the infection site release cytokines such as interleukin-1β (IL-1β), IL-8, and tumor necrosis factor-α (TNF-α) to induce the expression of P-, E-, and L-selectins on the luminal surface of endothelial cells." (PMID 27467389, 2016). "Although another study described a quite different immune response after intracardiac infection [mixed activating (IFNγ and TNFα)/deactivating (TGFβ) cytokine response], this route seems to be effective in term of infection persistence." (PMID 26969511, 2016). "Together in our infection model, these data suggest that both intracellular bacteria promote the NF-κB activation by cytosolic NLRs independently of the TNF-α-induced p65 phosphorylation." (PMID 27774437, 2016). "Compared to the A1142 parental strain, A1142::Ref-K57orf13 induced secretion of higher levels of TNF-α at 4 and 6 h post-infection." (PMID 27550826, 2016). "While these studies demonstrate the use of the TNF-α/IL-10 ratio as a biomarker, it has yet to be assessed in the context of trauma and infection prediction." (PMID 27761434, 2016). "Production of IFN-γ, TNF-α, and IL-6 suggests a type-1 proinflammatory response being developed shortly after infection, while IL-10 production can be related to immune regulation." (PMID 26989699, 2016). "Relative real-time qPCR on days 3 and 14 revealed that the expression of inflammatory markers, e.g. TNF-α, IL-28B and IL-29 were inducible during the infection." (PMID 27044429, 2016). "It is difficult to determine the usefulness of other cytokines, where IFN-γ and IL-10 were elevated late in the infection and the TNF-α, IL-1β, and IL-12p70 cytokines were randomly elevated and did not respond to oseltamivir." (PMID 27110056, 2016). "Similarly, in vitro infection of mouse bone marrow cells with highly pathogenic M. tuberculosis Beijing led to a stronger induction of expression of genes for the proinflammatory cytokines IL-1β, IL-12, and TNFα than did infection of cells with less virulent mycobacterial strains." (PMID 27066505, 2016). "In HLCs, the expressions of inflammatory cytokines, e.g., TNF-α, IL-28B and IL-29 were up-regulated during the infection that mimicked the natural infection in the primary hepatocytes." (PMID 27044429, 2016). "At 0.5 and 1 h of infection, the co-stimulation increased levels of p65 phosphorylation to 270% with respect to TNF-α alone and clearly higher than those values reached by S. flexneri infection alone." (PMID 27774437, 2016).
infection (continued). "Comprehensive cytokine/chemokine analysis reveals a host response to Ft largely similar between LVS and SchuS4 with significant levels of many factors (e.g., TNFα, IL-1β and IL-6) appearing at 3 dpi onwards during infection." (PMID 27015566, 2016). "TNFα and IL-1β levels were highest 24 h after infection and subsequently declined in the further course of culture." (PMID 26739172, 2016). "Levels of cytokine IL-1β and TNF-α in tissue homogenates was determined on different days post infection." (PMID 27333300, 2016). "In the process of control of the infection by mycobacteria, IL-12, IL-6, and TNF-α seem to have a primordial function." (PMID 27478636, 2016). "Further, M1 macrophages responded to infection with P. gingivalis with the production of TNF-α and IL-12, both cytokines important in initiating and regulating inflammation." (PMID 27383471, 2016). "Infection of epithelial cells by IFV increases the expression of TNF-α, IL-6, IL-8, CCL2 (MIP-1), CCL5 (RANTES), CCL3 (MIP-1α), and CXCL10 (IP-10)." (PMID 28066442, 2016). "Through studies employing anti-TNF-a drugs against rheumatoidarthritis, it has been documented that these drugs can favour the development orreactivation of infections by obligate intracellular microorganisms." (PMID 27759762, 2016). "Upon infection, they initiate inflammatory responses by releasing cytokines and chemokines, such as IL-1β, IL-18, TNF-α, and CCL3." (PMID 27043315, 2016). "As a pro-inflammatory cytokine, TNF-α is one of the early immune genes expressed at an early stage of infection in fish and has a key role in regulating inflammation." (PMID 27231948, 2016). "In mice, infection is shown to upregulate the proinflammatory cytokines such as interleukin 1β and TNF-α." (PMID 27891258, 2016). "While these data demonstrate that TNF blockade can prevent tissue damage during infection, they also highlight the importance of TNF for controlling parasite growth." (PMID 26765224, 2016). "TNF-α, a pro-inflammatory cytokine involved in recruitment of immune cells to the infection site, was detected at 8 h pt and then decreased at 24 h pt." (PMID 26193305, 2015). "The comparative equivalence of bacilli burdens in both the lungs and spleens of TNFf/f and NsTNF−/− mice during acute or chronic infection suggested a redundancy of neuron-derived TNF to contain cerebral spread of infection." (PMID 26112704, 2015). "The anti-TNF antibody Infliximab completely abrogated IFNγ effects on astrocyte infection by T. cruzi." (PMID 25695249, 2015). "Infection of M2 macrophages with C. pneumoniae resulted in significantly enhanced release of TNF-α, IL-6, IL12p70, IL-12p40, IL-10, CCL17, and CCL24 as compared to uninfected M2 cells." (PMID 26606059, 2015). "LCMV infection induced a very good titer of all the major proinflammatory cytokines (TNF, IL12p70, IL1β, IL-6) by day 7 that gradually decreased as infection proceeded." (PMID 26322025, 2015). "PAM at 6 h infection expressed TNF-α and IL-6 (pro-inflammatory cytokines) more highly with the two avian than the three mammalian influenza viruses." (PMID 26642934, 2015). "One hour after infection with ΔbgsA, plasma concentrations of TNF-α, IL-6, and MIP-2 were significantly increased in mice infected with ΔbgsA as compared to mice infected with wild-type bacteria or ΔbgsB." (PMID 26172831, 2015). "Although TNF-α production by CARD9−/− neutrophils and monocytes was impaired throughout the course of infection, defective TNF-α responses were only transient in the kidneys of CARD9−/− mice." (PMID 26336150, 2015). "Cytokine mRNA quantification showed increased levels of IFNγ, TNFα, IL-4, IL-6, and IL-12 during infection." (PMID 26481427, 2015). "In the WT mice there was a trend towards greater BALF levels of TNF-α, KC and IL-1β with the smooth compared to the rough infection, whereas in the CF mice this trend was reversed." (PMID 25675351, 2015).
infection (continued). "The temporal expression patterns of MR, IL-1β and TNF-α mRNAs were analyzed in the liver, spleen, kidney and intestine post of infection with Aeromonas sobria." (PMID 25988382, 2015). "The replacement of hepatic cells lost to infection, trauma, and inflammation is primarily mediated through IL-1 family cytokines, TNF-α, and IL-6 (all transcriptional targets of NF-κB) through their induction of the inflammatory acute phase response." (PMID 26635450, 2015). "Infection with AES-1M elicited a significantly higher TNF-α response than infection with AES-1R at both 3 and 24 hrs post infection (p<0.001)." (PMID 26252386, 2015). "In contrast, differences in cerebral bacilli burden were already significantly higher (p < 0.01) in TNF−/− mice at 2 weeks post-infection which were sustained at 3 weeks post-infection." (PMID 26112704, 2015). "At multiplicities of infection between 1:1 and 10:1, ΔbgsA induced significantly higher TNF-α concentrations compared to wild-type bacteria and ΔbgsB, respectively." (PMID 26172831, 2015). "We observed a positive correlation between the expression of TNF-alpha and the expression of Granzyme A only after the infection with Y strain." (PMID 26147698, 2015). "The attenuation of TNF-α was noteworthy as this suggests a role for C1q in control of host responses to infection." (PMID 26357509, 2015). "We also observed that production of TNF-α and IL-1β was reduced in exercising mice, while cathelicidin production was increased, suggesting that suppression of the infection by cathelicidin led to a decrease in cytokine production." (PMID 26542343, 2015). "Duck myotubes infected with the same high-pathogenicity virus displayed a weak proinflammatory response, with downregulation of TNF-α and IL-6 at 24 h of infection." (PMID 25540384, 2015). "Infection of WT mice by a virulent strain of C. albicans typically results in a 100-fold induction of TNF-α mRNA and several thousand fold induction of IL-6 mRNA." (PMID 26010544, 2015). "The presence of both IL-4 and IL-6 during the clearance phase of infection, when TNFα and IFNγ levels are exceedingly high, protects the colonic epithelial surface against more detrimental damage." (PMID 26481427, 2015). "Both subcutaneous MGAS315 and MGAS6180 infections induced very low levels of TNF-α but MGAS315 induced significant levels of IL-6 and low levels of IFN-γ in blood." (PMID 26047469, 2015). "High levels of TNFα are present in early stages of infection and in vivo neutralization of TNFα can prevent symptoms." (PMID 26599510, 2015). "These patterns of macrophage response were in contrast to those observed in MGL1+/+ macrophages, which showed a better proinflammatory response throughout the infection with higher production of TNF-α and NO in late infections compared to MGL1−/− macrophages." (PMID 25664320, 2015). "IFNγ and IL-12 mRNA were upregulated at all time points, whereas TNFα and IL-4 upregulation started at day 14 and IL-6 mRNA only increased at day 19 post infection." (PMID 26481427, 2015). "We then also investigated the role of internalized EphA2 for apoptosis resistance induced by infection with Ctr-serovar D. EphA2 silenced cells upon 16 h p.i. were sensitized for TNF-α/CHX-induced apoptosis determined by PARP cleavage." (PMID 25906164, 2015). "In this study, we initially demonstrated that global TNF is critical to control M. tuberculosis dissemination to the CNS and regulates immune-mediated brain pathology during infection." (PMID 26112704, 2015). "We found that in HepG2 cells TNF-α and FasL were induced robustly up to 36- and 21-fold at 72 hr p.i. in response to infection, but TRAIL remained mainly unchanged." (PMID 26134299, 2015). "Although TNF-α is vital for resistance against trypanosomosis, increasing TNF-α levels indicate a failing immune system and an uncontained infection." (PMID 26566996, 2015).